INTU (inturned planar cell polarity protein)
Description:
Plays a key role in ciliogenesis and embryonic development. Regulator of cilia formation by controlling the organization of the apical actin cytoskeleton and the positioning of the basal bodies at the apical cell surface, which in turn is essential for the normal orientation of elongating ciliary microtubules. Plays a key role in definition of cell polarity via its role in ciliogenesis but not via conversion extension. Has an indirect effect on hedgehog signaling (By similarity). Proposed to function as core component of the CPLANE (ciliogenesis and planar polarity effectors) complex involved in the recruitment of peripheral IFT-A proteins to basal bodies. Required for recruitment of CPLANE2 to the mother centriole (By similarity). Binds phosphatidylinositol 3-phosphate with highest affinity, followed by phosphatidylinositol 4-phosphate and phosphatidylinositol 5-phosphate (By similarity).
Synonyms: KIAA1284; PDZD6; PDZK6; CPLANE4; INT; OFD17; SRTD20
Tractability: Antibody: UniProt places it where antibodies can reach, with medium confidence. PROTAC: ubiquitination databases record sites on it.
Gene: Protein-coding gene on chromosome 4 (127,623,271 to 127,726,737, forward strand). Ensembl gene ENSG00000164066.
Subcellular location: Cytoplasm; Cell surface; Cytoplasm, cytoskeleton, cilium basal body; Cytoplasm, cytoskeleton, microtubule organizing center, centrosome, centriole
Subcellular location (Human Protein Atlas): Basal body; Cytosol; Vesicles
Pathways (Reactome):
Signal Transduction: Hedgehog 'off' state
Gene Ontology:
Molecular function: protein binding; phosphatidylinositol binding
Biological process: embryonic digit morphogenesis; roof of mouth development; tongue morphogenesis; cilium assembly; establishment of planar polarity; intraciliary transport; limb development; nervous system development; neural tube development; regulation of cilium assembly; regulation of smoothened signaling pathway; vesicle-mediated transport
Cellular component: ciliary basal body; motile cilium; cell surface; cilium; cytoplasm; centriole; ciliary transition zone
Genetic constraint (gnomAD): Loss-of-function variants: 53 observed, 65.86 expected, observed/expected ratio (o/e) 0.8, 90% interval 0.64 to 1.01. The upper end of that interval is the gene's LOEUF score, 1.01, which puts it in group 4 of 6, group 1 being the genes least tolerant of losing a copy. Missense variants: 782 observed, 857.88 expected, observed/expected ratio (o/e) 0.91, 90% interval 0.86 to 0.97. Synonymous variants: 258 observed, 310.44 expected, observed/expected ratio (o/e) 0.83, 90% interval 0.75 to 0.92.
Gene-disease validity (ClinGen):
ClinGen rates the evidence that INTU causes each of these diseases.
INTU-related skeletal ciliopathy (autosomal recessive): Definitive. A skeletal ciliopathy caused by a mutation in INTU gene and is characterized by facial dysmorphism, tongue nodules, developmental delay, and polydactyly.
Homologues: Orthologues: macaque INTU (98% identical), chimpanzee INTU (95% identical), dog INTU (89% identical), rabbit INTU (87% identical), guinea pig INTU (86% identical), pig INTU (85% identical), mouse Intu (79% identical), rat Intu (79% identical), tropical clawed frog intu (58% identical), zebrafish intu (52% identical), Drosophila melanogaster in (24% identical).
Diseases named in the same sentence as INTU in open-access papers:
INTU is named in the same sentence as 17 diseases in open-access papers, as found by Europe PMC text mining. Sharing a sentence is not in itself a finding about the gene and the disease. The quoted sentences say what the papers report.
basal cell carcinoma (2 papers, 2022 to 2023). A carcinoma involving the basal cells. "INTU is involved in Hedgehog signalling, a pathway activated in various cancers, including basal cell carcinoma, medulloblastoma and hematological malignancies." (PMID 37379307, 2023). "Inturned (INTU) is a PCP effector that reportedly functions synergistically with Hh signaling in basal cell carcinoma, suggesting that INTU has an oncogenic role." (PMID 36084949, 2022). "In basal cell carcinoma (BCC), INTU expression was aberrantly upregulated, accompanied by the induction of Hh signaling." (PMID 36084949, 2022).
ciliopathies (2 papers, 2020 to 2024). "Pathogenic variants in the ciliogenesis and planar cell polarity effectors (CPLANE) genes FUZZY, INTU and WDPCP disturb ciliogenesis, causing severe ciliopathies in humans and mice." (PMID 38546045, 2024). "It contains several proteins, such as INTU, FUZ, WDPCP, JBTS17 and RSG1 (REM2- and RAB-like small GTPase 1), whose genes are mutated in ciliopathies." (PMID 31562761, 2020).
endometriosis (1 paper, 2021). The growth of functional endometrial tissue in anatomic sites outside the uterine body. "The expression of INTU in 78 endometriotic tissue of women with endometriosis is associated with rs13126673 genotype (P = 0.034)." (PMID 33436679, 2021). "Moreover, we found that rs13126673 was at a novel locus on chromosome 4q28.1 with INTU and was associated with endometriosis." (PMID 33436679, 2021).
esophageal carcinoma (1 paper, 2022). A primary or metastatic malignant neoplasm involving the esophagus. "The results showed that the INTU transcription level was significantly downregulated in LUAD, LUSC and UCEC samples, whereas in esophageal carcinoma, KIRP, LIHC and SARC, no significant change of INTU expression between tumor and normal samples was detected." (PMID 36084949, 2022).
Hermansky-Pudlak syndrome (1 paper, 2020). Hermansky-Pudlak syndrome (HSP) is a multi-system disorder characterized by oculocutaneous albinism, bleeding diathesis and, in some cases, neutropenia, pulmonary fibrosis, or granulomatous colitis. "Using two contrasting evolutionary analyses, coevolution-based contact prediction and sequence conservation, we first identified the INTU/FUZ heterodimer as a novel member of homologous HerMon (Hermansky-Pudlak syndrome and MON1-CCZ1) complexes." (PMID 31562761, 2020).
lung adenocarcinoma (1 paper, 2022). A carcinoma that arises from the lung and is characterized by the presence of malignant glandular epithelial cells. "We found that the downregulation of INTU was associated with poor prognosis in lung adenocarcinoma (LUAD) and uterine corpus endometrial carcinoma (UCEC) patients." (PMID 36084949, 2022). "We demonstrated that INTU downregulation correlated with reduced survival probabilities in lung adenocarcinoma (LUAD) and uterine corpus endometrial carcinoma (UCEC) patients." (PMID 36084949, 2022).
lymphoid cancers (1 paper, 2023). "INTU was the only gene associated with lymphoid cancer after multiple testing correction for 43 genes with GnomAD exomes and 39 genes with ExAC controls." (PMID 37379307, 2023). "Three genes, INTU (p-value 0.004), PEX7 (p-value 0.02), and EHHADH (p-value 0.02) were associated with lymphoid cancers after multiple testing correction for 6 genes with ExAC controls." (PMID 37379307, 2023). "Four genes, INTU (p-value 0.005), ASXL1 (p-value 0.009), EHHADH (p-value 0.03) and PEX7 (p-value 0.02), were associated with lymphoid cancer after multiple testing correction for 7 genes when GnomAD exomes were used as controls." (PMID 37379307, 2023). "Stop-gain variant NM_015693.4:c.581G>A in INTU in the Hedgehog signalling pathway and stop-gain variant NM_000288.4:c.875T>A in PEX7 in peroxisomal pathway each segregated with lymphoid cancers in families, suggesting that these variants in these genes may be related to risk of lymphoid cancer." (PMID 37379307, 2023). "The genes EHHADH, INTU, PEX7, and ASXL1 were found to have a significantly higher burden of deleterious variants in cases than controls; variants in these genes may contribute to risk of lymphoid cancers in specific individuals." (PMID 37379307, 2023).
short rib-polydactyly syndrome (1 paper, 2022). Short rib-polydactyly syndromes are a group of bone malformations characterized by a narrow thorax and polydactyly (usually preaxial). "Recent literature has shown that mutations in INTU are causative for a short-rib polydactyly syndrome phenotype." (PMID 35873489, 2022).
tumor (2 papers, 2021 to 2022). "We next sought to explore the driving forces causing this downregulation in LUAD and UCEC tumor samples, and identified multifaceted mechanisms in the DNA, RNA and protein levels contributing to INTU and IFT88 downregulation." (PMID 36084949, 2022). "We therefore sought to delineate the underlying mechanisms of INTU and IFT88 downregulation in LUAD and UCEC tumor samples." (PMID 36084949, 2022). "The expression of INTU in tumor samples from The Cancer Genome Atlas (TCGA) were compared with that from normal samples from TCGA and The Genotype-Tissue Expression project (GTEx)." (PMID 36084949, 2022). "The results showed that relative to normal samples, proteins (ABCB4, FAM53B, and INTU) were significantly dysregulated in tumor tissues." (PMID 34717651, 2021). "Moreover, the expression of MALAT1 was found to be positively associated with the mRNA levels of INTU and IFT88 in LUAD and UCEC tumor samples." (PMID 36084949, 2022). "A group of Hh pathway-related genes, including INTU and intraflagellar transport 88 (IFT88), were enriched in LUAD and UCEC tumor samples." (PMID 36084949, 2022). "Taken together, this study demonstrates the prognostic significance of the Hh-related genes INTU and IFT88 in LUAD and UCEC and further delineates multifaceted mechanisms leading to INTU and IFT88 downregulation in tumor samples." (PMID 36084949, 2022). "Altogether, TCF4 was identified as a putative upstream regulator in controlling the expression of INTU and IFT88 in LUAD and UCEC tumor samples." (PMID 36084949, 2022). "Moreover, we demonstrated novel TCF4 and ncRNA-involved mechanisms that contribute to the downregulation of INTU and IFT88 in LUAD and UCEC tumor samples." (PMID 36084949, 2022). "In addition, INTU expression significantly correlated with the expression of IFT88 from LUAD and UCEC tumor samples." (PMID 36084949, 2022).
INTU also shares sentences with these, for which no sentence is quoted: acromelic frontonasal dysostosis (1 paper); breast carcinoma (1); cancer (1); endometrial cancer (1); hematological malignancies (1); medulloblastoma (1); thoracic aortic aneurysm (1); uterine corpus endometrial carcinoma (1).